GSK3B (glycogen synthase kinase 3 beta)
Diseases named in the same sentence as GSK3B in open-access papers (continued):
Sharing a sentence is not in itself a finding about the gene and the disease.
glioblastoma (continued). "The GSK3β inhibitor AR-A014418 effectively counteracted the effects of GAD1 knockdown, suppressing the enhanced proliferation, cell cycle progression, and invasion of glioblastoma cells, while also reducing the expression of p-GSK3β, β-catenin, Cyclin D1, and MMP9." (PMID 41844572, 2026). "TAM-derived legumain exerts dual regulatory roles in glioblastoma (GBM) by promoting macrophage infiltration in an autocrine manner via the GSK3β/STAT3 pathway, while in a paracrine fashion, TAM-secreted legumain drives GBM cell proliferation and survival through integrin αv/AKT/p65 signaling." (PMID 41417432, 2025). "The smaller hub, GSK-3β, integrates signals from mutations in NF1 and PTEN, as well as from the Wnt, sortilin, and EGF pathways, playing an important role in glioblastoma pathogenesis." (PMID 39857717, 2025). "Additionally, GSK3β plays an essential role in glioblastoma carcinogenesis and is involved in brain function through the modulation of various processes, such as neuronal morphology, synapse formation, neuroinflammation, and neurological disorders." (PMID 39518976, 2024). "Interestingly, GSK3β regulates c-Myc itself, and our previous research has connected AURKA activity to c-Myc levels in a GSK3β-dependent manner in model systems of glioblastoma, involving both adult and pediatric model systems." (PMID 38995006, 2024). "In conclusion, chrysomycin-A may inhibit the proliferation, migration, and invasion of glioblastoma cells through the Akt/GSK-3β/β-catenin signaling pathway." (PMID 38396785, 2024). "Furthermore, downregulation of Akt, p-Akt, GSK-3β, p-GSK-3β, and their downstream proteins β-catenin and c-Myc, was also observed in human glioblastoma cells." (PMID 38396785, 2024). "RIP-qPCR experiments demonstrated that YTHDF2 binds to APC and GSK-3β mRNAs in glioblastoma cells." (PMID 38637831, 2024). "Also, a combination regime of OLZ and other GSK3β-inhibitors improves the prognosis of patients with refractory glioblastoma." (PMID 39054537, 2024). "Inhibition of GSK-3β by miR-101 also sensitizes glioblastoma to TMZ." (PMID 36755314, 2023). "In addition, endosomal mTORC2 is required for Akt-dependent FOXO1/3a and GSK3β phosphorylation in Glioblastoma cells." (PMID 38135881, 2023). "Meanwhile, downregulation of GSK-3β, p-GSK-3β, β-catenin and their downstream, c-Myc and cyclin D1 using the Chr-A treatment indicates that Chr-A may exert anti-glioblastoma activity by downregulating the Akt/GSK-3β/β-catenin pathway." (PMID 36234681, 2022). "PI3K-activated Akt could inactivate GSK-3β followed by multiple downstream effects; thus, we proposed the hypothesis that Chr-A may inhibit glioblastoma through the Akt/GSK-3β/β-catenin pathway." (PMID 36234681, 2022). "In conclusion, Chr-A may inhibit the proliferation, migration and invasion of glioblastoma cells through the Akt/GSK-3β/β-catenin signaling pathway." (PMID 36234681, 2022). "In contrast, nuclear GSK-3β is not only responsible for cancer stem cell self-renewal and glioblastoma tumorigenesis by stabilizing histone demethylase KDM1A but also crucial for acute myeloid leukemia (AML) initiation and aggressiveness in AML via β-catenin independent mechanisms." (PMID 35646902, 2022). "Previous research revealed that GSK3B could promote DNA repair resulting in chemo- and radiotherapy resistance in glioblastoma." (PMID 35756487, 2022). "GSK3β has been reported to promote invasion in glioblastoma and therapy resistance in cancer." (PMID 36408180, 2022). "However, a growing body of research has established the role of GSK-3β as a protooncogenic protein itself, particularly in the context of ovarian cancer, acute leukemias, glioblastoma, neuroblastoma, and PDAC." (PMID 34356465, 2021).
glioblastoma (continued). "GSK-3β is an important hub of different signaling cascades and its activity is involved in differentiation and migration of embryonic/adult neural stem cells and differentiation of cancer cells with stem cell-like characteristics, such as glioblastoma cells." (PMID 32903776, 2020). "Besides, ENMD-2076 induces glioblastoma cells apoptosis via inhibiting Akt/GSK3β/β-catenin signaling pathway." (PMID 31706255, 2019). "Furthermore, we proved that sortilin promoted cell invasion mainly via Glycogen synthase kinase 3 beta (GSK-3β)/β-catenin/Twist-induced EMT-like mesenchymal transition in glioblastoma." (PMID 30814514, 2019). "However, in contrast, a tumor-promoting role of GSK3β has been reported in leukemia, glioblastoma, non-small cell lung cancer, BON-1, insulinoma and H727 cells as well as medullary thyroid carcinoma cells." (PMID 28800359, 2017). "In contrast to its effects against several proto-oncoproteins (eg., β-catenin, cyclin D1) and mediators of epithelial-mesenchymal transition in untransformed cells, we have found that deregulated GSK-3β facilitates the progression of gastrointestinal cancers and glioblastoma." (PMID 27780915, 2016). "Conversely, it was reported that GSK3β sustains tumor cell stemness in leukemia and glioblastoma." (PMID 23408967, 2013). "Recently, the pathologic role of GSK3β in malignant brain tumor was investigated, and it was found that it could protect glioblastoma cells from apoptosis by promoting survival and proliferation." (PMID 22046442, 2011). "In glioblastoma (GBM) stem cells, palmitoylation Glycogen synthase kinase 3β (GSK3β) at Cys14 mediated by ZDHHC4 can activate STAT3 signaling to improve the stemness of temozolomide (TMZ)-resistant GBM." (PMID 39877903, 2025). "In temozolomide (TMZ)-resistant glioblastoma multiforme (GBM), miR-101 downregulation led to GSK3β upregulation, promoting O6-methylguanine-DNA methyltransferase (MGMT) expression and resistance, while miR-101 overexpression sensitized cells to TMZ." (PMID 40074445, 2025). "Fractionated IR activates the Wnt/β-catenin/GSK3β/P62 pathway, promoting autophagic activity and enhancing radioresistance in glioblastoma (GBM)." (PMID 38671354, 2024). "Chrysomycin A (Chr-A) has been reported to inhibit the proliferation, migration and invasion of U251 and U87-MG cells through the Akt/GSK-3β signaling pathway, but the mechanism of Chr-A against glioblastoma in vivo and whether Chr-A modulates the apoptosis of neuroglioma cells is unclear." (PMID 37367654, 2023). "In addition to this, as a selective autophagy receptor, p62 could promote EMT of glioblastoma cells through targeting GSK‐3β for degradation." (PMID 35676831, 2023). "Thus, Chr-A may function against glioblastoma via apoptosis regulation in the Akt/GSK-3β signaling pathways in vivo and in vitro, confirming the KEGG enrichment analysis above." (PMID 37367654, 2023). "Furthermore, we revealed that Chr-A could exert anti-glioblastoma activity through the Akt/GSK-3β/β-catenin pathway." (PMID 36234681, 2022). "Furthermore, we found that quercetin suppressed GSK-3β/β-catenin/ZEB1 signaling in glioblastoma." (PMID 36386155, 2022). "The decrease in DAP12 expression level in shKLRC3 cells associated with the significant decrease in the GSK3β protein strongly supports the hypothesis of a link between KLRC3 and DAP12 in the regulation of the glioblastoma aggressiveness, particularly in the radioresistance phenotype." (PMID 27641066, 2017). "Glycogen synthase kinase (GSK)-3β has emerged as an appealing therapeutic target for glioblastoma (GBM)." (PMID 28423558, 2017). "Moreover, miRNA-101 reverses temozolomide resistance by inhibition of GSK3β in glioblastoma." (PMID 28742860, 2017). "Inhibitor studies were conducted using selective inhibitors of Cdk5 and GSK3β to understand their contributions to CRMP-2 modulation, enabling the evaluation of how changes in CRMP-2 phosphorylation affected glioblastoma cell proliferation and migration." (PMID 40283503, 2025).
glioblastoma (continued). "Thus, Chr-A may exert anti-glioblastoma activity in vivo via the Akt/GSK-3β signaling pathway." (PMID 37367654, 2023). "In this sense, it has been recently reported in glioblastoma that GSK3β expression leads to NDRG1 degradation as a tumor suppressor and, conversely, NDRG1 overexpression induced GSK3β degradation as a bidirectional regulatory mechanism." (PMID 36594086, 2023). "9-ING-41, a small-molecule, selective GSK3β inhibitor, showed preclinical activity in chemo-resistant PDX glioblastoma models, including enhanced lomustine antitumor effect." (PMID 35402914, 2022). "In U251 glioblastoma-derived cell line interaction between VIM and GSK3β was demonstrated with implications in cell migration; HeberFERON modified phosphorylation on both proteins." (PMID 36552831, 2022). "In this study, we screened a library of 22 anti-invasive compounds (i.e., NF-kB, GSK-3-B, COX-2, and tubulin inhibitors) using glioblastoma U-251 MG cell spheroids." (PMID 34639060, 2021). "In astrocytoma grade II, 30% of samples had methylated GSK3β promoter, followed by 27% of astrocytoma grade III and 10% of glioblastoma." (PMID 34064046, 2021). "Finally, a more general role for GSK3B in drug resistance can be proposed given that several studies indicated GSK3B as an actionable target for the treatment of drug-resistant carcinomas derived not only from colon but also from kidney, pancreas, endometrium and for glioblastomas." (PMID 34065438, 2021). "Proscillaridin A acts as the activator for GSK3β by reducing the EB1 comet length and inhibition of glioblastoma migration at relatively less concentration." (PMID 32784680, 2020). "Peiminine induces cell cycle arrest through inhibiting Akt-GSk3β signaling pathway, and decreases autophagic flux via depressing AMPK-ULK1 signaling pathway in glioblastoma multiforme cells." (PMID 32131410, 2020). "For instance, downregulation of GSK3β could re-sensitize drug-resistant cells to chemotherapy, enhanced expression of GSK3 is associated with acquired resistance to paclitaxel in ovarian cancer, and GSK3β inhibition can sensitize human glioblastoma cells to TMZ." (PMID 27792996, 2016). "The effects of Akt were thought to be mediated by the activation of the Wnt/β-catenin pathway and GSK3β phosphorylation in mammary stem/progenitor cells, and by Akt-induced ABCG2 activation in glioblastoma stem-like cells." (PMID 25625591, 2015). "We hypothesized that YTHDF2 in glioblastoma could bind to m6A sites on APC and GSK-3β mRNAs, promoting their degradation and activating the Wnt-β-catenin pathway." (PMID 38637831, 2024). "Importantly, the protein levels of USP22, GSK3β, and LSD1 were found to be positively correlated with one another and concurrently increased in the nuclei of glioblastoma and glioma stem cells (GSCs)." (PMID 39394462, 2024). "Furthermore, Chr-A also down regulated Akt, p-Akt, GSK-3β, p-GSK-3β and their downstream proteins, such as β-catenin and c-Myc in human glioblastoma cells." (PMID 36234681, 2022). "Furthermore, decreased expression of Akt-affected GSK-3β and their downstream proteins including β-catenin, c-Myc and cyclin D1 in U251 and U87-MG cells after Chr-A treatment for 48 h implied that Chr-A may exert an anti-glioblastoma action via the Akt/GSK-3β/β-catenin signaling pathway in vitro." (PMID 36234681, 2022). "Interestingly, GPNMB expression in melanoblasts and osteoclasts was shown to be dependent on MITF, and in human glioblastoma cells this transcription factor is activated by PI3K/Akt and GSK3β signaling." (PMID 25889792, 2015).
glioblastoma (continued). "To determine if VPA treatment inhibits GSK3β in HT22 hippocampal neurons and GL261 glioblastoma cells, we monitored the phosphorylation of GSK3β at ser9 that inhibits its activity and evaluated the levels of β-catenin as a surrogate indicator of GSK3β activity." (PMID 26413814, 2015). "The inhibition of GSK-3β has been shown to complement the function of CD28 as a costimulatory molecule in the proliferation of human T cells and has been found to prolong the survival and enhance the anti-tumor cytotoxicity of chimeric antigen receptor T cells in the setting of a glioblastoma model." (PMID 34356465, 2021). "For instance, metformin modulates the synergistic regulation between AMPK, GSK-3β, and PPAR-γ that confer its anti-angiogenic, anti-invasive, and anti-proliferative as observed in pancreatic cancer and glioblastoma multiforme (GBM)." (PMID 31831021, 2019). "Tideglusib, a non-ATP-competitive GSK-3β inhibitor, has been tested in xenograft and PDX murine models of human glioblastoma." (PMID 32526891, 2020). "Phosphorylated GSK3β levels were low in UW479, Res259 and Res186, and almost entirely absent in the glioblastoma lines SF188 and KNS42." (PMID 19365568, 2009). "Similarly, the inhibition of GSK-3β in glioblastoma (GBM)-specific IL13 chimeric antigen receptor expressing T (IL13-CAR-T) cells increased the survival and proliferation of CAR-positive T cells upon activation with IL13Rα2-expressing GBM tumor cells, or soluble target antigen." (PMID 32526891, 2020). "Finally, GSK3B, PNKP and RB1, which were suggested as targets to control the neuroinflammation in response to WNV infection in the glioblastoma cell line U251, were not modulated in our study." (PMID 32374750, 2020).
melanoma (119 papers, 2009 to 2025). A malignant, usually aggressive tumor composed of atypical, neoplastic melanocytes. "We observed a significant increase in GSK3β mRNA expression in A375 BRAF-mutated melanoma cells during the development of BRAF resistance." (PMID 40184329, 2025). "By blocking the ADAM17/EGFR/AKT/GSK3β pathway, RA prevents invasive proliferation and migration of human melanoma A375 cells, induces apoptosis, and increases the susceptibility of melanoma cells to cisplatin." (PMID 40427522, 2025). "SNAI2 has been directly implicated in melanoma progression by triggering the activation of the GSK-3β/β-catenin pathway." (PMID 37511550, 2023). "Nobiletin, a citrus peel-derived flavonoid, causes ferroptosis of melanoma cells which is down-regulated by GSK3β knockdown." (PMID 36139919, 2022). "Accordingly, Slug is required for metastatic spread of the transformed melanoma cells, and GSK3β inhibition was associated with increased Slug and N-cadherins expression and prevented melanoma cells interaction with stromal cells and migration." (PMID 24550888, 2014). "Mechanistically, IR-546 activated GSK-3β Ser9 phosphorylation, which suppressed β-catenin and its downstream proteins in vitro and in vivo, thereby inhibiting melanoma growth through suppression of the AKT/GSK-3β/β-catenin pathway." (PMID 40495167, 2025). "Collectively, these findings highlight IR-546 as a promising tool for both imaging and treatment of melanoma, with the potential to induce apoptosis and inhibit metastasis of melanoma through modulation of the AKT/GSK3β pathway." (PMID 40495167, 2025). "Third, various methods, including GSK3β overexpression and knockdown assays, are needed to elucidate the biological consequences of p-GSK3β upregulation in melanoma tissues." (PMID 41153674, 2025). "In this study, we observed upregulation of p-GSK3β in melanoma tissue samples ex vivo, as demonstrated by Western blot analysis." (PMID 41153674, 2025). "Here we set out to investigate the impact of GSK3β on the development of BRAF inhibitor (BRAFi) resistance in melanoma." (PMID 40184329, 2025). "Nonetheless, even though GSK3β’s involvement in cancer biology is well recognized, there is a notable paucity of studies addressing GSK3β expression specifically in human melanoma tissues." (PMID 41153674, 2025). "Western blot analysis revealed that ArcA treatment led to a marked reduction in the levels of phosphorylated GSK-3β (p-GSK-3β) at Ser9 across all four melanoma cell lines." (PMID 39948552, 2025). "Prior studies have shown that Kaempferol (KAM) inhibits melanoma metastasis by impairing glycolysis through the AKT/GSK-3β pathway." (PMID 40495167, 2025). "Immunofluorescence analysis revealed a remarkable increase in the phosphorylation levels of PI3K, Akt, and GSK3β in fisetin-treated cells (20, 40 μM), compared with both melanoma and α-MSH-stimulated melanoma cells." (PMID 41373883, 2025). "Though its oncogenic role is poorly understood, first indirect evidence showed that GSK3β activation protected melanoma cells from apoptosis, whereas its inhibition prevented mouse melanoma cell growth both in vivo and in vitro." (PMID 40184329, 2025). "Molecular docking studies were conducted in the different proteins (Fz4-CRD, LRP6, GSK3β) of the Wnt signaling pathway and Protein Kinase B/Akt for the isolated compound to investigate the possible pathway to inhibit melanoma." (PMID 40341615, 2025). "The levels of p-GSK3β were found to be significantly elevated in all melanoma tissue samples relative to normal tissues." (PMID 41153674, 2025). "Although our findings strongly support CA’s therapeutic potential in melanoma via GSK3β modulation, this study possesses certain limitations that must be addressed." (PMID 41153674, 2025). "The journal retracts the article, “GSK-3β-Targeting Fisetin Promotes Melanogenesis in B16F10 Melanoma Cells and Zebrafish Larvae through β-Catenin Activation”, cited above." (PMID 41363996, 2025).